IDH1 (isocitrate dehydrogenase (NADP(+)) 1)
Diseases named in the same sentence as IDH1 in open-access papers (continued):
Sharing a sentence is not in itself a finding about the gene and the disease.
glioma (continued). "Using lentiviral transduction, we induced exogenous mutant IDH1 R132H protein expression in the wildtype IDH1 glioma cell line, MOG-G-UVW (MOG-R132H)." (PMID 29062039, 2017). "Recently, molecular biomarkers including 1p/19q co-deletion, BRAF mutation, IDH1/2 mutation, and TERT mutation have been widely used for glioma diagnosis, treatment, and prognosis prediction." (PMID 28978019, 2017). "We analyzed 112 IDH1 wild-type (IDH1WT) versus 399 IDH1MUT low-grade glioma and 157 IDH1WT versus 9 IDH1MUT glioblastoma samples." (PMID 28467784, 2017). "The role of Nrf2 in IDH1 R132H overexpressing cells provides new insight for glioma treatment in the future." (PMID 28427200, 2017). "While genetic alterations such as EGFR amplification and CDKN2A deletion are common in IDH1 WT gliomas, they rarely occur in gliomas with mutant IDH1." (PMID 28178660, 2017). "Glioma survival is strongly associated with the IDH1/IDH2 mutation, with IDH1 wild-type typically being associated with poorer outcomes." (PMID 29099032, 2017). "A study of gliomas, which also display the CpG island methylator phenotype (G-CIMP), demonstrated that the introduction of a single mutation in IDH1 into primary human astrocytes rearranges the epigenome to match G-CIMP tumours." (PMID 28351398, 2017). "Much like other targeted therapies for genetically defined patient populations, IDH1 mutant gliomas appear to be selectively sensitive to 2-HG inhibition in order to elicit an anti-tumor response." (PMID 29062039, 2017). "IDH1-mutated U87MG glioblastoma and NCH644 glioma stem-like cells display significantly enhanced phosphorylation of AMPK." (PMID 29057925, 2017). "However, the mechanism of IDH1 mutations on the chemosensitivity of glioma remains unclear." (PMID 28427200, 2017). "A series of inhibitors was reported to have promising preclinical efficacy and early-phase clinical activity in IDH1/2 mutant glioma and AML cells." (PMID 29184081, 2017). "5-Azacytidine induced tumor regression in a patient-derived IDH1 mutant glioma xenograft model;198 while 5-aza-2′-deoxycytidine effectively suppressed growth in IDH-mutant glioma cells in vitro and in vivo." (PMID 28092669, 2017). "The results suggested that IDH-1 wild-type glioma possessed more active angiogenesis and less heterogeneous microenvironment." (PMID 29097933, 2017). "Notwithstanding, certain types of glioma have proven hard to maintain in vitro even when cultured in the presence of serum, such as the IDH1 mutant gliomas." (PMID 28978189, 2017). "Both IDH1 and IDH2 mutations were identified in ∼15% of gliomas, which were predominantly seen in grade II-III gliomas and secondary glioblastomas." (PMID 29290954, 2017). "In our study, we used a panel composed of IDH1/1p19q/TERT which is worldwide recognized in the precise diagnosis of glioma to demonstrate the anatomic distribution of different molecular subsets." (PMID 28915860, 2017). "The effects of IDH1 and IDH2 mutations on α-ketoglutarate flux and accumulation of 2-hydroxyglutarate leading to altered intracellular signaling in glioma cells, have been extensively reviewed elsewhere." (PMID 28491867, 2017). "Compared to their wild type counterparts, IDH1 mutant gliomas have a favorable clinical response to TMZ and IDH1 has become an important prognostic factor." (PMID 28178660, 2017). "An efficacy study was performed using GB10 to assess intracranial IDH1 mutant glioma growth inhibition following MRK-A treatment." (PMID 29062039, 2017). "Mutations have also been identified in isocitrate dehydrogenase 1 (IDH1) that inhibit IDH1 catalytic activity in gliomas, thereby reducing the production of α-KG, inhibiting PHD, increasing HIF-1α, and presumably, promoting tumorigenesis." (PMID 27058900, 2016).
glioma (continued). "The latest evaluation of molecular subgroups of gliomas identified ATRX, CIC, and FUBP1 mutations, and allowed distinguishing patients with IDH1/CIC/FUBP1 or IDH1/ATRX mutations." (PMID 27834917, 2016). "Mutations in the metabolic proteins IDH1 and IDH2 are associated with gliomas, acute myeloid leukemias, chondrosarcomas, intrahepatic cholangiocarcinomas, lymphomas, melanomas and colon, thyroid and prostate cancers." (PMID 26971564, 2016). "Another study reported that the expression of BCAT1 was significantly reduced in IDH1 MT glioma cells compared with their wild-type counterparts, and it was investigated by hyperpolarized 13C magnetic resonance spectroscopy (MRS)." (PMID 27626306, 2016). "After gene transfer into F98 glioma cell lines with lentiviral vectors containing IDH1/2–WT–GFP, IDH–R132H/–R172K–GFP, or empty–mock–GFP expression codons, GFP–expressing F98 cells represented ~95.8–99.1% of the total population." (PMID 26820720, 2016). "First, we used a Gene Set Enrichment Analysis (GSEA) to compare the global gene expression profiles of the IDH2 mutant and IDH1 mutant gliomas." (PMID 27245697, 2016). "Among 811 gliomas in our cohort, 448 cases (55.2 %) harbored an IDH1 mutation, 18 cases (2.2 %) harbored an IDH2 mutation and 345 cases (42.6 %) harbored an IDH1/2 wild-type." (PMID 27245697, 2016). "The IDH1/2 gene mutations, ATRX loss/mutation, 1p/19q status, and MGMT promoter methylation are increasingly used as prognostic or predictive biomarkers of gliomas." (PMID 27834917, 2016). "Detection of the IDH1-R132H mutation should help in the differential diagnosis of grade II and III gliomas from other types of CNS tumors and help determine the boundary between the tumor and normal brain tissue." (PMID 27877908, 2016). "We used F98 glioma cells transfected with human IDH1/2 gene–cloned lentiviral vectors and implanted in rat brain." (PMID 26820720, 2016). "In this study, we collected 211 serial sampling of gliomas and detected ATRX and IDH1-R132H status in the progression of gliomas by immunohistochemistry." (PMID 26918938, 2016). "IDH1 and 2 alterations exist in several tumors including gliomas and more recently identified in BTCs through high throughput molecular profiling." (PMID 27102149, 2016). "Recurrent IDH1-mutant patient gliomas had a stiffer TNC-enriched ECM that our studies attributed to reduced miR-203 suppression of HIF1α and TNC mediated via a tension-dependent positive feedback loop." (PMID 27820599, 2016). "IDH1 and IDH2 are mutated in >75% of low grade gliomas and secondary glioblastoma multiforme (GBM), and 20% of AML." (PMID 27548812, 2016). "Gain- and loss-of-function xenograft manipulations demonstrated that a mutant IDH1 restricts glioma aggression by reducing HIF1α-dependent TNC expression to decrease ECM stiffness and mechanosignalling." (PMID 27820599, 2016). "Mutations in the IDH1 and IDH2 genes have been found in patients with gliomas and were initially identified in low-grade gliomas and secondary glioblastomas." (PMID 27245697, 2016). "Taken together, our study shows that reduced MCT expression is part of the metabolic reprogramming of mutant IDH1 gliomas." (PMID 27144334, 2016). "Isocitrate dehydrogenase 1 (IDH1) and IDH2 genes are frequently mutated in low-grade gliomas, denovo acute myeloid leukemias in adult and in the subsets of chondrosarcomas and lymphomas." (PMID 27377127, 2016). "The effectiveness of this method was explored using IDH1/2 and BRAF mutations in clinical glioma samples." (PMID 27529619, 2016). "IDH1/2 mutations are seen in patients with cytogenetically normal AML, MDS, MPN, angioimmunoblastic T-cell lymphoma, glioma, cholangiocarcinoma, and chondrosarcoma." (PMID 27023522, 2016).
glioma (continued). "The result will help to evaluate the progressive pattern and time interval of patients with the initial gliomas using the reference histology combined with IDH1-R132H and ATRX status." (PMID 26918938, 2016). "A subset of leukemia cells with mutations in the metabolic enzymes isocitrate dehydrogenase 1 (IDH1) and 2 (IDH2), and IDH1-mutant glioma cells have been shown to be particularly sensitive to glutaminase inhibition." (PMID 27806325, 2016). "In recent years, mutations in isocitrate dehydrogenase 1 (IDH1) and IDH2 have been shown to characterize low-grade glioma and secondary glioblastomas." (PMID 26911558, 2016). "We analyzed glioblastoma cell lines with known MGMT activity and formalin-fixed samples from IDH1 wild-type high-grade glioma patients (WHO grade III/IV) treated with radiation and temozolomide by HRM, MSP, and pyrosequencing." (PMID 27158275, 2016). "The association between MGMT promoter methylation and clinical outcome (using a 5 % cut-off value) comparing HRM, MSP, and PSQ was analyzed in tumor material of 65 IDH1 wt glioma patients (seven gliomas grade III and 58 grade IV)." (PMID 27158275, 2016). "Patients with IDH2 mutant gliomas exhibited longer Overall survival (OS) (p < 0.05) and longer Progression-free survival (PFS) (p < 0.05) than patients with IDH1/2 wild-type gliomas." (PMID 27245697, 2016). "Our findings contribute to the understanding of mutant IDH1 cell metabolism and have important implications for the treatment and imaging of mutant IDH1 gliomas." (PMID 27144334, 2016). "Given the DNA methylation profiles of 3 IDH2 mutant gliomas and 41 IDH1 mutant gliomas, we used standard t-tests to identify differentially methylated regions." (PMID 27245697, 2016). "We then compared the whole-transcriptome sequencing expression profiles of the IDH2 mutant and IDH1/2 wild-type gliomas." (PMID 27245697, 2016). "The area under roc curve (AUC) of using IDH1-R132H as a diagnostic biomarker for discriminating between pGBM and grade II/III glioma, sGBM was 0.7414 (sensitivity 63.19%, specificity 85.09%)." (PMID 26918938, 2016). "Preclincial studies have shown that the DNA methylation inhibitor 5-aza-2′-deoxycytidine (5-azadC) effectively reverses DNA hypermethylation observed in IDH1 mutant gliomas, induces tumor stem cell differentiation, and inhibits tumor growth in mouse models." (PMID 26646321, 2016). "We analyzed the cohort of patients with primary and recurrent gliomas to observe the value of IDH1-R132H or ATRX as biomarkers evaluating the progression-free survival of patients with gliomas." (PMID 26918938, 2016). "In low-grade gliomas and secondary GBM, highly recurrent mutations are observed in a key metabolic enzyme, isocitrate dehydrogenase-1 (IDH1)." (PMID 27588472, 2016). "Mutations in IDH1 and IDH2 regard the majority of low-grade gliomas in adults, defining a subtype associated with a better prognosis." (PMID 27338365, 2016). "We here present a novel heterozygous IDH1 mutation, IDH1R314C, which was identified by targeted next generation sequencing of a high grade glioma from which a mouse xenograft model and a cell line were generated." (PMID 27460417, 2016). "To this end, we have assessed the performance of the conventional short TE 1H–MRS in the detection of 2HG in a rodent model of IDH1/2 mutant–overexpressing F98 glioma at 9.4T." (PMID 26820720, 2016). "This group displays rare Tert promoter mutations (10 %); however, IDH1 and IDH2 mutations (75 %) as well as ATXR mutations (70 %) are common, which is also correlated with the high prevalence of ALT (63 %) in these gliomas." (PMID 26846696, 2016). "Among these, the strongest signal arose from increased tumor mtDNA content in IDH1-mutant low grade gliomas (BH-corrected p-value 0.012)." (PMID 26901439, 2016).
glioma (continued). "TET2 mutations in various myeloid cancer, or mutations of IDH1 and IDH2 in low-grade gliomas, which can inhibit DNA hydroxymethylation by TET enzymes, have been reported and cause DNA hypermethylation phenotype." (PMID 27829228, 2016). "Decitabine can efficiently induce the differentiation and growth inhibition in IDH1 mutant glioma cells." (PMID 27557118, 2016). "A recent study reported that IDH1-R132H expression correlates positively with angiogenesis and cell proliferation in glioma samples." (PMID 27655638, 2016). "IDH1 mutations were found in ~75 % low-grade gliomas as well as secondary glioblastoma multiforme (GBM), the grade IV glioma developed from the low-grade tumors." (PMID 27316347, 2016). "The promoter methylation of O-6-methylguanine-DNA methyltransferase (MGMT) and IDH-1 have been designated as meaningful molecular biomarkers for glioma in the National Comprehensive Cancer Network (NCCN) guidelines." (PMID 27763568, 2016). "Mutations in isocitrate dehydrogenase 1 (IDH1) and isocitrate dehydrogenase 2 (IDH2) are frequent in low-grade gliomas and secondary glioblastomas (sGBM)." (PMID 27245697, 2016). "Heterozygous missense mutations affecting IDH1 and IDH2 were found in gliomas and in acute myeloid leukaemia (AML)." (PMID 27117029, 2016). "Although, association with tumor grade was not analyzed in our study due to the small number of low grade glioma, we found two risk variants in the CDKN2A and CDKN2B regions associated with mutated IDH1." (PMID 26839018, 2016). "The IDH1 c.G395A; p.R132H mutation was associated with longer survival in grade II astrocytoma, glioblastoma, and pooled groups of patients with WHO grade II glioma." (PMID 27834917, 2016). "We illustrated an evaluation formula for the evolution of gliomas by IDH1-R132H combined with ATRX immunohistochemistry and identified the association of IDH1-R132H/ATRX loss accompanied by longer progression time interval of patients with gliomas." (PMID 26918938, 2016). "We compared the mutational landscapes of IDH1 and IDH2 mutant gliomas, their clinical associations, overall survival, and progression-free survival." (PMID 27245697, 2016). "We found that the mean normalized z-scores of mRNA expression were significantly reduced for both MCT1 (0.22 vs. −0.21, p<0.05) and MCT4 (0.25 vs. −0.15, p<0.005) in mutant IDH1 glioma samples (n=218) compared to wild-type IDH1 low-grade glioma (n=68)." (PMID 27144334, 2016). "In conclusion, our results describe the clinical and biological characteristics of IDH1 and IDH2 mutations in gliomas." (PMID 27245697, 2016). "Mutations in the metabolic enzymes IDH1 and IDH2 are frequently found in glioma, cholangiocarcinoma, T-cell lymphomas, thyroid cancer, chondrosarcoma, and AML." (PMID 27806325, 2016). "Genome-wide methylation study further identified a subset of adult glioblastoma with glioma-CpG island methylation phenotype (G-CIMP) which was enriched in proneural subgroup, tightly associated with IDH1 mutation and exhibiting favorable prognosis." (PMID 26452024, 2016). "In our laboratory, we incubated two IDH1 mutant glioma models with [1-13C]-glucose and [3-13C]-glutamine and analyzed the proportion of 13C-labeled 2-HG derived from each precursor." (PMID 27014635, 2016). "PFS was significantly longer in patients with grade II gliomas harboring IDH1-R132H than in patients with IDH1 wild-type tumors (Median PFS of IDH1-R132H = 893 days, Median PFS of IDH1-wt = 580 days, p = 0.0009, log-rank test)." (PMID 26918938, 2016). "Increasing evidences have demonstrated that IDH1 mutations and MGMT methylation are associated with survival benefit in gliomas." (PMID 26556853, 2016). "Consistently, IDH1-mutant tumours exhibit DNA hypermethylation in gliomas and leukemia, and histone hypermethylation." (PMID 27117029, 2016). "Combined IDH1 and IDH2 mutations were found in 14.6 % (30/205) of pGBM, 58.6 % (17/29) of sGBM and 72.6 % (419/577) of low grade gliomas." (PMID 27245697, 2016).
glioma (continued). "Previous findings demonstrated that chemotherapy does not prolong OS in patients with isocitrate dehydrogenase 1-mutant (IDH1 mut) tumors in low grade gliomas." (PMID 27677590, 2016). "A previous study revealed impairment of glioma cell growth by a mutant IDH1 inhibitor, which is anticipated to be utilized for future molecular-targeted therapy." (PMID 27529619, 2016). "Mutations in the IDH1 or IDH2 genes are found in the majority of adult diffuse grade II and grade III gliomas and are considered as the earliest oncogenic event in these tumors." (PMID 27036230, 2016). "Of particular interest is that all these mutations occur exclusively in the R132 residue of IDH1 or the corresponding R172 residue of IDH2, with the R132H mutation being predominant (>90 %) in these gliomas." (PMID 27316347, 2016). "These criteria, which set a stringent level (at least > 55% of tumor cells) for the definition of the 1p/19q codeletion by FISH, identified all IDH1/2 mutated and ATRX wild type gliomas that meet the 2016 WHO Criteria for OGs." (PMID 28030632, 2016). "We also found that IDH1-R132H and ATRX expression status of the recurrent tumor was most consistent with that of their initial tumor and that IDH1-R132H positive gliomas had a significantly longer progression-free survival (PFS)." (PMID 26918938, 2016). "A phase I trial of AG-120, an oral inhibitor of mutant IDH1, demonstrated stable disease in 10 of 20 patients with IDH1-mutant glioma, with a 6-month clinical benefit response rate of 25%." (PMID 27556016, 2016). "Mutant IDH1 glioma cells, however, display reduced PC levels indicating that they reprogram choline metabolism differently." (PMID 27144334, 2016). "The IDH1/2 mutations, 1p/19q status and MGMT promoter methylation are commonly recognized biomarkers in patients with gliomas." (PMID 27834917, 2016). "Subsequently, another study showed the presence of mutated IDH1 (R132) and IDH2 (R172) genes in a majority of grade II or III gliomas and in secondary glioblastomas." (PMID 26668680, 2016). "Among 262 cases from lower-grade glioma and 235 cases from glioblastoma with complete sequencing and CNA data, a total of 216 cases with an IDH1 mutation and available information about histological grade were analyzed." (PMID 26524630, 2015). "Vehicle gliomas appeared immune-reactive for IDH1-R132H, whereas gliomas from immunized mice almost completely lost IDH1-R132H expression, as also confirmed by RT-PCR." (PMID 25849072, 2015). "Mutations in IDH1 and/or IDH2 have been identified in gliomas as well as in hematological malignancies." (PMID 25823555, 2015). "Sensitivity to ETO was then tested in other glioma cell lines overexpressing either IDH1 or IDH1R132, LN18 and T98." (PMID 25811801, 2015). "Consistently, inhibition of mutant IDH1 was recently reported to have preclinical efficacy in IDH1 mutant glioma cells and IDH2 mutant AML." (PMID 25825982, 2015). "Mutations in IDH1 or IDH2 are frequently observed in human cancers, particularly with high frequency in secondary glioma, acute myeloid leukemia, and chondrosarcoma." (PMID 25825982, 2015). "Our data thus confirmed that the IDH1 mutation more frequently occurred in low-grade gliomas (Grade II and III) than in high-grade gliomas (Grade IV), in accordance with previous reports." (PMID 26485760, 2015). "TCGA network has further identified a distinct subgroup of GBM called a glioma-CpG island methylator phenotype (G-CIMP), which belonged to the proneural subgroup and was tightly associated with IDH1 somatic mutation." (PMID 25669971, 2015). "Mutant IDH1/2 causes hypermethylation of the genome via inhibition of α-ketoglutarate dependent enzymes in AML, gliomas, enchondromas and chondrosarcomas." (PMID 25895133, 2015).